PDCD4 (programmed cell death 4)
Diseases named in the same sentence as PDCD4 in open-access papers (continued):
Sharing a sentence is not in itself a finding about the gene and the disease.
tumor (continued). "A xenotransplant of SW480 overexpressing miRNA-181b into SCID mice produced tumours with increased weight, size and cellular proliferation, which was rescued by overexpressing miRNA-181b-insensitive PDCD4." (PMID 35847932, 2022). "Programmed cell death 4 (PDCD4) was first thought to be a tumor suppressor gene, which played an anti-tumor effect by promoting apoptosis and inhibiting tumor cell proliferation, invasion, and metastasis." (PMID 35573679, 2022). "A comparison between tumours and adjacent normal tissue has shown there is an inverse correlation between miRNA-21- and PDCD4 expression in GI cancers." (PMID 35847932, 2022). "PDCD4 inhibits protein translation PDCD4 inhibits protein translation to suppress tumor progression, and its expression is frequently decreased in breast cancer." (PMID 35795053, 2022). "These include the tumour suppressors, PDCD4, RB1, STK2, transcriptional regulators with reported roles in cancer, BCL9L, STAT5B and proteins that are involved in control of the cell cycle, ANAPC4, ANAPC5, RBX1." (PMID 35573784, 2022). "The bioinformatics analysis of miR-21 predicted targets suggested that multiple tumor suppressor genes, including programmed cell death 4 (PDCD4), tropomyosin (TPM1), PTEN, and Fork-head box O1 (FoxO1) related to apoptosis pathways, have miR-21 binding sites." (PMID 36180486, 2022). "The subsequent ubiquitination targets PDCD4 for proteasomal degradation and ultimately promotes tumor formation." (PMID 35795053, 2022). "Both NFκB-driven and exosomal miR-21a was shown to silence PDCD4, a tumor suppressor and IL-6 inhibitor, promoting the expansion of MDSCs in a IL-6/STAT3 dependant manner in lung cancer." (PMID 35320943, 2022). "PDCD4 was initially suggested to be a tumor suppressor in transformation-resistant JB6 cells because the down-regulation of PDCD4 expression by antisense RNA resulted in a gain of transformation-susceptible phenotype." (PMID 35795053, 2022). "In contrast, the tumor suppressor PDCD4 turned out to be a much more consistent miR-21 target across mouse and human models." (PMID 35053428, 2022). "In vivo, PDCD4-deficient effector CD8 T cells also exhibited increased IFNγ production in tumor models, resulting in delayed tumor growth." (PMID 34983947, 2022). "Studies have shown that miR-208b secreted by CRC cells is sufficiently delivered to receptor T cells to promote Treg amplification, tumor growth and oxaliplatin resistance by targeting programmed cell death factor 4 (PDCD4)." (PMID 35574420, 2022). "Transfection and overexpression of PDCD4 suppresses the tumour phenotype in RT101 (JB6) epidermal cells and inhibits AP-1-dependent transcription needed for this phenotype." (PMID 35847932, 2022). "Aside from these, TGF-β can activate apoptotic events by stimulating the expression of programmed cell death 4 (PDCD4), a novel tumor suppressor gene that is frequently inactivated in HCC." (PMID 35205692, 2022). "Although PDCD4 is a confirmed tumour suppressor, little is known about how the protein suppresses tumorigenesis." (PMID 35847932, 2022). "Programmed cell death protein 4 (PDCD4) is an important tumor suppressor and has been reported to prevent AKT activation and to be involved in miR-21-repressed cell apoptosis in AD models." (PMID 35173580, 2022). "Several validated miR-21 target genes are tumor suppressors, e.g., programmed death protein 4 (PDCD4)." (PMID 35657974, 2022). "As a tumor suppressor, PDCD4 has multi-functions including inhibiting cell growth, tumor invasion, metastasis, and inducing apoptosis." (PMID 35983977, 2022). "miR-21 is able to negatively regulate phosphatase and tensin homologue deleted on chromosome ten (PTEN), tropomyosin 1 (TPM1), and apoptosis protein 4 (PDCD4), which in turn induces tumor cell growth, migration, invasion, and metastasis." (PMID 35216464, 2022).
tumor (continued). "Programmed cell death 4 (PDCD4) acts as a tumor suppressor regulated by miRNA-21 and has an inhibitory effect on cell proliferation by blocking protein translation." (PMID 35295323, 2022). "While PTEN reduces tumor growth and affects PI3K/Akt/mTOR signaling pathway, PDCD4 is involved in many cellular functions and behaviors such as tumor growth, apoptosis, invasion and cell transformation." (PMID 35682901, 2022). "The tumours from these cells had decreased PDCD4 expression, increased mitosis, decreased apoptosis and elevated size and weight." (PMID 35847932, 2022). "Later, several additional studies demonstrated that PDCD4 not only inhibits tumor promoter-induced transformation but also suppresses cancer cell proliferation, migration, invasion, and metastasis (for detail please see reviews)." (PMID 35795053, 2022). "Although examining the downregulation of PDCD4 in tumours has become increasingly common, only a relatively few publications have shown how the expression of the protein is regulated." (PMID 35847932, 2022). "Understanding how these and endogenous miRNAs are orchestrated will be fundamental in determining how tumour suppressors such as PDCD4 are regulated in vivo." (PMID 35847932, 2022). "Programmed cell death 4 (PDCD4) is an important tumor suppressor through inhibiting protein initiation complex formation." (PMID 35983977, 2022). "The role of miR-21-5p lies in its specific targeting of the three prime UTR (3′-UTR) of PDCD4, which negatively regulates protein expression and is a well-known tumor suppressor." (PMID 35282462, 2022). "They observed that this co−delivery strategy effectively inhibited the growth and metastasis of tumor cells via the upregulation of tumor suppressor genes PDCD4 and PTEN and the inhibition of epithelial–mesenchymal transition." (PMID 36234452, 2022). "It inhibits PDCD4 protein synthesis which decreases eIF4A hence promoting cell growth, tumor invasion, metastasis, and inhibiting cell apoptosis." (PMID 35895593, 2022). "Subsequent to the discovery that PDCD4 acts as a tumour suppressor in JB6 cells, the protein was found to inhibit translation and bound the eukaryotic translation-initiation factor 4A (eIF4A)." (PMID 35847932, 2022). "Programed cell death receptor 4 (PDCD4) is described as a tumor suppressor, which is often down-regulated in tumors, promoting tumor cell apoptosis and inhibiting its proliferation, invasion and metastasis." (PMID 35910224, 2022). "Their results also demonstrated that miR-21 promoted cystic growth, possibly through direct repression of Programmed cell death 4 (PDCD4), a novel tumor suppressor that promotes apoptosis." (PMID 35205236, 2022). "PDCD4 modulates several signal transduction pathways and impacts the translation and transcription of many genes as a tumor suppressor." (PMID 34925466, 2021). "For instance, programmed cell death 4 (PDCD4), a tumor suppressor, is methylated at Arg110 by PRMT578." (PMID 34006904, 2021). "One of the suppression mechanisms of tumor formation by PDCD4 occurs through the translation inhibition of a set of genes involved in proliferation, invasion, and metastasis of tumor cells." (PMID 34606825, 2021). "PDCD4 can inhibit neoplastic transformation, tumor angiogenesis and invasion, and/or induce apoptosis." (PMID 33801444, 2021). "Programmed cell death 4 protein (PDCD4) regulates many vital cell processes, although is classified as a tumor suppressor because it inhibits neoplastic transformation and tumor growth." (PMID 34606825, 2021). "a. phosphatase and tensin homolog (PTEN) and programmed cell death protein 4 (PDCD4), which have a suppressive effect, the reduced activity of which results in inhibition of tumor cell apoptosis and the acquisition of invasive properties." (PMID 34680441, 2021). "In conclusion, we demonstrated that circ-ITCH was a tumor suppressor in ccRCC via miR-106b-5p/PDCD4 pathway." (PMID 33969128, 2021).
tumor (continued). "The regulatory function of miR-21 depends on its target genes such as PTEN and PDCD4 (programmed cell death 4), which are both tumor suppressors." (PMID 33917022, 2021). "HuR and TIA-1 can also interact to impact mRNA encoding programmed cell death 4 (PDCD4), a tumor suppressor that induces apoptosis." (PMID 34769392, 2021). "miR-21 activated the PI3K/AKT and NF-κB signaling pathways, leading to initial inflammation; thereafter, miR-21 and TNF-α repressed PDCD4 and its tumor suppression activity." (PMID 34771727, 2021). "PDCD4 is a new type of tumor suppressor that has multiple functions of inhibiting cell growth, tumor invasion, metastasis, and inducing apoptosis." (PMID 34885115, 2021). "There are two mechanisms for decorin-dependent control of inflammation and tumor growth that are based on either stimulation of PDCD4 (programmed cell death protein 4) expression, or on it translational repression." (PMID 34917515, 2021). "Programmed cell death 4 (PDCD4) is a proinflammatory tumor-suppressor gene which helps to prevent the transition from chronic inflammation to cancer." (PMID 33288677, 2021). "Programmed Cell Death 4 (PDCD4) is a gene whose role is defined as being involved in battling against neoplastic diseases by inducing translational suppression of mRNA." (PMID 34946938, 2021). "In particular, MSC-EVs enriched in miR-208a are taken up by SAOS2 and MG63 cells, which inhibited programmed cell death 4 (PDCD4) eventually stimulating tumor cells proliferation, migration and invasion." (PMID 34616676, 2021). "In this study, we found a highly expressed circRNA in BC, hsa_circ_0053063 and then we exposed it as a tumor suppressor via negative regulating miR-330-3p expression to activate PDCD4." (PMID 33744861, 2021). "Tumour suppressor PDCD4 competes with EIF4A for binding to EIF4G1, as such inhibiting the initialization of translation." (PMID 33523588, 2021). "We further characterized PDCD4 expression on immune cells in the tumor stroma, as little is known in this area." (PMID 33801444, 2021). "To assess the independent predictive value of PDCD4 expression in tumor and stroma, we performed Cox proportional hazards analysis, which included as covariates treatment information and BRAF/NRAS mutational status." (PMID 33801444, 2021). "In tumor cells, PDCD4 shuttles between the two compartments, and its nuclear localization and total protein expression are lost during disease progression." (PMID 33801444, 2021). "miR-21 is a negative regulator for TLR4 to activate NF-κB and decrease IL-10 production by targeting a pro-inflammatory tumor suppressor PDCD4." (PMID 33618723, 2021). "For instance, reduced levels of PDCD4 promote tumor cell invasion, and this can influence the development of neck nodal metastasis in the OSCC." (PMID 34946938, 2021). "PDCD4 is a tumor suppressor, and its expression is frequently down-regulated in various types of cancers." (PMID 33726686, 2021). "Programmed cell death protein 4 (PDCD4) is an important tumor suppressor that plays a vital role in cellular oxidative stress." (PMID 34506261, 2021). "This is in agreement with previous studies showing that miR-21 and miR-27a acted as cooperative repressors of a network of tumor suppressor genes that included PDCD4, BTG2, and NEDD4L." (PMID 34208765, 2021). "Programmed cell death 4 (Pdcd4) is a novel tumor suppressor due to its role in inhibiting carcinogenesis, tumor progression and invasion." (PMID 32203159, 2021). "PDCD4 acts as a tumor suppressor by inhibiting malignant transformation, tumor progression, and metastasis." (PMID 33288677, 2021). "PDCD4 is known as one tumor suppressor gene which inhibits cell proliferation, tumor angiogenesis and induces apoptosis." (PMID 33762949, 2021). "PDCD4 is involved in apoptosis and inhibits tumor progression by acting on eIF4A and eIF4G, suppressing mRNA translation whereas PTEN diminishes the P13K/Akt/mTOR signaling pathway which results in tumor growth." (PMID 33768115, 2021).
tumor (continued). "This provided a partial explanation to the re-sensitization of Osimertinib since PDCD4 is a major tumor suppressor to repress several oncogenic cascades such as c-Myc, Bcl-xL, and mTOR/Akt." (PMID 34885115, 2021). "CK2 was already shown to interact with PDCD4 within the nucleus with their expression levels being inversely correlated in the tumor setting." (PMID 34917890, 2021). "Programmed cell death 4 (Pdcd4), is a novel tumor suppressor to show multi-functions inhibiting cell growth, tumor invasion, metastasis, and inducing apoptosis." (PMID 34917083, 2021). "Programmed cell death 4 (PDCD4) is a tumor suppressor and an apoptotic activator whose expression has been shown to be upregulated following PI3K/AKT inhibition leading to subsequent elevation of cell cycle inhibitor p27 in several malignancies." (PMID 34359600, 2021). "Future studies will focus on the interaction of PLEKHA5 and PDCD4 and the critical role of PDCD4 on boosting anti-tumor responses and survival in brain metastases." (PMID 33801444, 2021). "Programmed cell death protein 4 (PDCD4) exerts critical functions as tumor suppressor and in immune cells to regulate inflammatory processes." (PMID 34917890, 2021). "Then, PDCD4 suppressed anti-inflammatory mediators such as IL-10, which creates a proinflammatory tumor microenvironment, thus retarding tumor growth." (PMID 34888227, 2021). "Programmed cell death 4 (PDCD4) is a proinflammatory tumor suppressor gene which regulates apoptosis of cells in response to inflammatory stimuli." (PMID 33288677, 2021). "PDCD4 (programmed cell death 4) is a tumour suppressor gene that not only inhibits proliferation, migration and invasion but also promotes apoptosis in tumours." (PMID 33270982, 2021). "PDCD4 is a tumor suppressor in BC, and the expression level of PDCD4 correlates positively with the level of antisense lncRNA PDCD4-AS1." (PMID 34461912, 2021). "The tumor suppressor PDCD4 protects cells from neoplastic transformation, exhibits reduced expression levels in malignant compared to non-transformed cells, and functions to inhibit protein translation." (PMID 34070147, 2021). "For instance, miR-21 is a tumor-promoting miRNA because it decreases the expression of tumor-suppressive genes, including PDCD4 and PTEN, and promotes the progression of gastrointestinal cancers." (PMID 34830186, 2021). "Studies showed that PDCD4 was downregulated in RCC patients and strongly associated with tumor stage, tumor grade, tumor metastasis, and tumor-related death." (PMID 33969128, 2021). "PDCD4 is a well-known tumor suppressor regulating the growing, invading, or metastasis of the tumors." (PMID 34925466, 2021). "It is well documented that decreased PDCD4 expression is closely related to the enhanced proliferation, survival and metastasis of tumor cells." (PMID 33078826, 2020). "In the same way, miR-10b was described as an oncomiR in BC by targeting tumor suppressive genes (e.g., PDCD4, PTEN, TPM1), thus promoting proliferation, invasion and metastasis, and predicting the worst BC prognosis." (PMID 32842653, 2020). "Our current understanding of the function of human PDCD4 derives mostly from work carried out with transformed tumor cells." (PMID 32066800, 2020). "The finding that PDCD4 is required for the G1/S-transition seems counterintuitive considering that PDCD4 expression is often decreased in tumor cells." (PMID 32066800, 2020). "PDCD4, one of the targets of miR-21, was demonstrated to be a tumor-suppressor gene and the target of procancer miRNAs (Lankat-Buttgereit and Göke, 2009)." (PMID 33329700, 2020). "Concomitantly, miR-21-5p offers a strong predictive value, for example, with regard to overall patient survival, as also seen for the protein tumor suppressors, e.g. BTGs and PDCD4, identified or confirmed here to be regulated by this miRNA." (PMID 34316687, 2020).
tumor (continued). "A large body of work has suggested that down-regulation of PDCD4 expression contributes to tumor development by stimulating the mobility and the metastatic potential of tumor cells." (PMID 32066800, 2020). "Dysregulation of PDCD4 alters the levels of several proteins involved in cell cycle, tumor progression, apoptosis, and differentiation in tumor cells." (PMID 33304903, 2020). "Our current understanding of PDCD4′s role in human cells is largely based on studies using transformed tumor cell lines." (PMID 32066800, 2020). "We previously showed that PDCD4 protein was phosphorylated at S67, S71, and S76 via the tumor promotor EGF and TPA-mediated signaling pathways and degraded by the ubiquitin-proteasome system." (PMID 31952347, 2020). "In contrast to GAS5, miR-21 was highly expressed in tumour tissues compared to peritumoral tissues, while the trend in PDCD4 expression was the same as that in GAS5 expression." (PMID 32661236, 2020). "eIF4A is frequently activated in neoplasia, either through mRNA overexpression or suppression of the tumor suppressor protein PDCD4 (programmed cell death 4), which competes with eIF4G for binding to eIF4A." (PMID 32517051, 2020). "Programmed cell death protein 4 (PDCD4) is a tumor suppressor responsible for the inhibition of cell growth, tumor invasion, metastasis, or induction of apoptosis." (PMID 32340207, 2020). "It has been reported that the up-regulation of PDCD4 sensitizes tumor cells to anti-tumor drugs, such as gemcitabine, cisplatin, tamoxifen, and geldanamycin." (PMID 33304903, 2020). "On the other way, upregulation of miR-21 in NSCLC enhances KRAS-driven tumor initiation via repressing tumor suppressors including programmed cell death 4 (PDCD4) and apoptosis peptidase activating factor 1 (APAF1)." (PMID 32316322, 2020). "As it was mentioned, PDCD4 diminishes the viability and proliferation of tumor cells by stimulation of programmed cell death." (PMID 32612456, 2020). "The identification of a pro-proliferative role for PDCD4 in the cell cycle is somewhat unexpected in the light of its function as a tumor suppressor." (PMID 32066800, 2020). "The up‐regulation of PDCD4 was discovered in cells undergoing apoptosis, and PDCD4 has been shown to act as a novel tumour inhibitor and its down‐regulation is observed in many cancers." (PMID 33089961, 2020). "PDCD4 (programmed cell death 4) is a tumor suppressor that plays a crucial role in multiple cellular functions, such as the control of protein synthesis and transcriptional control of some genes, the inhibition of cancer invasion and metastasis." (PMID 31952347, 2020). "PDCD4, a well-known tumor suppressor upregulated in our study, has been suggested to interact with c-JUN, blocking c-JUN phosphorylation by JNK." (PMID 32260415, 2020). "The PDCD4 acts as a tumor-suppressor gene and performs essential functions in many biological events, including apoptosis, protein translation, signal transduction, and stimulation of inflammattion mediators." (PMID 33304903, 2020). "For example, three tumor suppressors, including programmed cell death 4 (PDCD4), phosphatase, and tensin homolog (PTEN), and reversion-inducing cysteine-rich protein with Kazal motifs (RECK), have been shown to be regulated by miR-21 in CCA." (PMID 33007962, 2020). "Decorin signaling suppressed tumor growth by stimulating PDCD4, shifting the immune response toward a proinflammatory phenotype in a tumor xenograft model." (PMID 32825245, 2020). "When tumor cells over-expressing PDCD4 were injected into nude mice, the increased expression of PDCD4 blocked tumorigenesis and prolonged overall survival." (PMID 33304903, 2020). "The over-expression of PDCD4 decreases anchorage-independent growth in vitro, and prevents tumor growth in the xenograft mouse model." (PMID 33304903, 2020). "Previous studies have revealed the cell cycle inhibitory and apoptosis-inducing roles of PDCD4, so PDCD4 has been regarded as a tumor suppressor." (PMID 31952347, 2020).